MMUT (methylmalonyl-CoA mutase)
Diseases named in the same sentence as MMUT in open-access papers (continued):
Sharing a sentence is not in itself a finding about the gene and the disease.
amyotrophic lateral sclerosis (1 paper, 2022). Amyotrophic lateral sclerosis (ALS) is a neurodegenerative disease characterized by progressive muscular paralysis reflecting degeneration of motor neurons in the primary motor cortex, corticospinal tracts, brainstem and spinal cord. "Multivariable Mendelian randomization revealed that the toxic effect of isoleucine is dependent on the depletion of vitamin B12; consistent with this, rare variants which reduce the function of MMUT are protective against amyotrophic lateral sclerosis." (PMID 35441136, 2022).
cardiomyopathy (1 paper, 2017). A disease of the heart muscle or myocardium proper. "The disturbance of propanoate metabolism (deficiency of methylmalonyl-CoA mutase, propionyl-CoA carboxylase and malonyl-CoA decarboxylase) can cause many metabolic diseases characterized by developmental delay, seizure, hypoglycemia, cardiomyopathy and malonic aciduria." (PMID 28808302, 2017).
cblC (1 paper, 2025). "Indeed, glutathione metabolism has been shown to be disturbed in the related disorder cobalamin deficiency type C (cblC), in which the production of the cofactor of MMUT is disturbed." (PMID 40436252, 2025).
colorectal adenocarcinoma (1 paper, 2024). The most common type of colorectal carcinoma. "MMUT deficiency was introduced via CRISPR knockout (KO) in foreskin fibroblast (HFF1), colorectal adenocarcinoma (HT-29), and lymphoblast (K562) cell lines." (PMID 39128713, 2024).
Insulin resistance (1 paper, 2024). Increased resistance towards insulin, that is, diminished effectiveness of insulin in reducing blood glucose levels. "Previous studies showed a downregulation of BCAA degradation pathway genes, including PCCA/B and MMUT, in insulin resistance/T2DM, while a GWAS noted an association between insulin resistance and a region downstream of MMUT." (PMID 38271099, 2024).
malnutrition (1 paper, 2015). Inadequate nutrition resulting from poor diet, malabsorption, or abnormal nutrient distribution. "The mechanisms that cause deficiency are malabsorption, malnutrition or genetic deficiency of methylmalonyl-CoA mutase." (PMID 26385097, 2015).
neuroblastoma (1 paper, 2018). Neuroblastoma (NB) is the most common solid, extracranial childhood tumor. "In summary, the proteomic characterization of a methylmalonyl-CoA mutase-silenced neuroblastoma cell line allowed us to define a dataset of deregulated proteins and relative alterated cellular pathways that may be investigated to highlight the unknown molecular mechanism underlying MMA damage." (PMID 30428564, 2018).
renal dysfunction (1 paper, 2021). "A kidney transplant is often required as well as LT due to the high expression of the methylmalonyl CoA mutase activity in the kidney and MMA‐associated renal dysfunction." (PMID 34258144, 2021).
Stillbirth (1 paper, 2024). Death of the fetus in utero after at least 22 weeks of gestation. "We investigated the MTRDHH1 haplotype, which substantially increased stillbirth rate, and identified a single nucleotide variant (SNV) inducing a premature stop codon (p.Gln409*) in the methylmalonyl-CoA mutase (MMUT) gene by using a whole-genome sequencing approach." (PMID 38424485, 2024).
metabolic disorder (16 papers, 2007 to 2025). "MMA is a metabolic disorder most commonly caused by mutations in the methylmalonyl-CoA mutase (MMUT) gene." (PMID 36126056, 2022). "Methylmalonic acidemia (MMA) is an autosomal recessive metabolic disorder mainly caused by mutations in the methylmalonyl coenzyme A mutase (MCM) gene (MMUT) and leads to the reduced activity of MCM." (PMID 35919035, 2022). "The metabolic disorder commonly results from mutations in the methylmalonyl-CoA mutase (MUT) gene." (PMID 17470278, 2007). "The new strategy identified the opportunity to reclassify these variants in MMUT and MMACHC in the current database and may enable us to prioritize and target the pathogenicity of variants in other inherited metabolic diseases for evaluation." (PMID 39076170, 2024). "MMA is an autosomal recessive metabolic disorder resulting from a deficiency of the enzyme methylmalonyl-CoA mutase or a lack of its cofactor, adenosyl-cobalamin (vitamin B12)." (PMID 39518591, 2024). "Patients with metabolic disorder-related genes (ALDH5A1 and MMUT) are known to develop neurological disorders; however, seizures are not always the first or the most remarkable symptom requiring medication." (PMID 34992632, 2021).
cancer (5 papers, 2020 to 2025). A tumor composed of atypical neoplastic, often pleomorphic cells that invade other tissues. "Third, from our in silico gene deletion analysis, we identified Sterol O-Acyltransferase 1 (SOAT1), methylmalonyl-CoA mutase (MUT), and isozymes of succinate dehydrogenase (SDHA, SDHB, SDHC, and SDHD) as having a significant effect (p-value < 0.05) in cancer as compared to normal samples." (PMID 33396819, 2020).
mitochondrial disease (4 papers, 2020 to 2025). "We further investigate diseases specifically affecting the mitochondria and take the dysfunction of the mitochondrial matrix residing metabolic enzyme methylmalonyl-coenzyme A mutase (MMUT) as a paradigm of mitochondrial disease." (PMID 34524466, 2021).
MMUT also shares sentences with these, for which no sentence is quoted: cobalamin deficiency (3 papers); homocystinuria (3); macrocytic anemia (2); phenylketonuria (2); tumor (2); anemia (1); Chronic tubulointerstitial nephritis (1); cyst (1); cystic fibrosis (1); developmental delay (1); Diabetes (1); Failure to thrive (1); genetic disorder (1); hemophilia A (1); Hydrocephalus (1); Hypercalcemia (1); Hypoglycemia (1); infection (1); kidney (1); leukopenia (1); lung carcinoma (1); megaloblastic anemia (1); melanoma (1); nesidioblastosis (1); neurological disorders (1); Obesity (1); organic acid metabolic disorder (1); pneumonia (1); respiratory failure (1); tuberculosis (1).